KCNMA1 (potassium calcium-activated channel subfamily M alpha 1)
Diseases named in the same sentence as KCNMA1 in open-access papers (continued):
Sharing a sentence is not in itself a finding about the gene and the disease.
gastric cancer (3 papers, 2014 to 2019). A primary or metastatic malignant neoplasm involving the stomach. "Ma and collaborators have previously shown that the overexpression of KCNMA1 in the human gastric cancer cell lines, MGC803 and BGC823, was associated with a significant reduction in their invasion and migration properties and inhibited the tumor growth in a xenograft murine model." (PMID 30791468, 2019). "In contrast, KCNMA1 is down-regulated or silenced in primary cells and in gastric carcinoma cell lines (MGC-803, BGC-823, MKN-82, SGC-7901), through hyper-methylation of its promoter, in particular, the CpG island, cg24113782." (PMID 30791468, 2019). "We further investigated the putative tumor suppressor function of KCNMA1 in human gastric cancer both in vitro and in vivo assays." (PMID 28231797, 2017). "KCNMA1 significantly inhibited biological malignant behavior of gastric cancer cell by inducing cell apoptosis in vitro, and suppressed xenograft tumor growth in subcutaneous mouse models (both P < 0.001)." (PMID 28231797, 2017). "In the present study, we have identified that KCNMA1 is commonly silenced or down-regulated in primary gastric cancer tissues and gastric cancer cell lines due to promoter hypermethylation." (PMID 28231797, 2017). "In conclusion, we have identified a novel tumor suppressive gene, KCNMA1, which is frequently inactivated in gastric cancer because of promoter methylation." (PMID 28231797, 2017). "The CpG site cg24113782 located at the promoter of KCNMA1 showed the most significant difference, contributing to the commonly silenced KCNMA1in gastric cancer cells and primary GC tissues." (PMID 28231797, 2017). "KCNMA1 is a critical tumor suppressor in gastric carcinogenesis and its hypermethylation is an independent prognostic factor in patients with gastric cancer." (PMID 28231797, 2017). "The mechanism by which KCNMA1 suppressed malignant behaviors of the gastric cancer cell was mediated by inducing cell apoptosis." (PMID 28231797, 2017). "KCNMA1 is down-regulated in gastric carcinoma tumors, through hypermethylation of its promoter." (PMID 30791468, 2019). "We found that the gene, potassium channel, calcium activated large conductance subfamily M alpha, member 1(KCNMA1), the function of which remains largely unexplored, was moderated by promoter methylation in gastric cancer." (PMID 28231797, 2017). "Accordingly, KCNMA1 overexpression was not sufficient to inhibit the migration and invasion of gastric cancer cells after PTK2 knockdown." (PMID 30791468, 2019). "Similarly, inhibitory ability on gastric cancer cell migration and invasion was also attenuated by si-PTK2, that is, KCNMA1 did not have the ability to suppress migration and invasion of gastric cancer cells after PTK2 was knockdown." (PMID 28231797, 2017).
malignant pleural mesothelioma (3 papers, 2016). A malignant neoplasm that arises from mesothelial cells in the pleura and shows a diffuse growth pattern. "Calcium-activated potassium channel subunit alpha-1 (KCNMA1) was overexpressed in malignant pleural mesothelioma (MPM), and KCNMA1 downregulation suppressed the migration of MPM cells." (PMID 27811365, 2016).
pulmonary hypertension (3 papers, 2014 to 2022). Increased pressure within the pulmonary circulation due to lung or heart disorder. "Biomarker genes for pulmonary hypertension included PRKG1, KCNMA1, FOXO1, and NOS3." (PMID 35740428, 2022).
adenoma (2 papers, 2019 to 2023). A neoplasm arising from the epithelium. "We collected the resected carcinoma tissues from CRC patients and conducted immunohistochemical (IHC) staining analysis to examine the expression of some representative genes including NEK8, CHRM3, ANO7, B3GNT6, NEURL1, ODC1 and KCNMA1 in colon normal tissue, adenoma tissue and carcinoma tissues." (PMID 36944972, 2023). "The analysis of the methylation profile and the Principal Components Analysis (PCA) (Table A1) show that the DNA methylation pattern of the KCNMA1 gene allows to differentiate the normal colonic mucosa from adenoma and from adenocarcinoma, with and without liver metastases." (PMID 30791468, 2019).
age related hearing loss (2 papers, 2010 to 2021). "Although no current genetic-based studies linking KCNMA1 SNP to presbycusis and aging exist, BK channels appear to be sensitive to oxidative stress." (PMID 33336302, 2021).
angioedema (2 papers, 2020 to 2023). Swelling involving the deep dermis, subcutaneous, or submucosal tissues, representing localized edema. "The KCNMA1 intron 1 variants significantly associated with angioedema in our study lack evidence of functional activity, but are in linkage disequilibrium with several genetic variants located in regulatory elements." (PMID 32080354, 2020). "Genetic variants in the calcium-activated potassium channel subunit alpha-1 (KCNMA1) gene were significantly associated with angioedema on a genome-wide level (p < 5 × 10−8)." (PMID 32080354, 2020). "In summary, our data suggest that common variation in KCNMA1 is associated with risk of angioedema induced by ACEi or ARB treatment." (PMID 32080354, 2020). "Our GWAS suggests that common genetic variants of KCNMA1 are associated with risk of ACEi- or ARB-induced angioedema." (PMID 32080354, 2020). "The calcium-activated potassium channel subunit alpha-1 (KCNMA1) gene on chromosome 10 was significantly associated with angioedema on a genome-wide level." (PMID 32080354, 2020). "In the genome-wide analysis, intronic variants in the calcium-activated potassium channel subunit alpha-1 (KCNMA1) gene on chromosome 10 were significantly associated with angioedema (p < 5 × 10−8)." (PMID 32080354, 2020). "Future whole exome or genome sequencing studies will show whether rare variants in KCNMA1 or other genes contribute to the risk of ACEi- and ARB-induced angioedema." (PMID 32080354, 2020). "Furthermore, meta-analysis of four cohorts of cases and treated controls supported the association between KCNMA1 and ACEi- or ARB-induced angioedema." (PMID 32080354, 2020).
atrial fibrillation (2 papers, 2020 to 2024). A disorder characterized by an electrocardiographic finding of a supraventricular arrhythmia characterized by the replacement of consistent P waves by rapid oscillations or fibrillatory waves that vary in size, shape and timing and are accompanied by an irregular ventricular response. "A loss‐of‐function mutation in the Kcnma1 gene is associated with tachy‐brady syndrome and atrial fibrillation." (PMID 38561252, 2024). "In humans, the Kcnma1 gene is positioned within the first locus mapped from familial atrial fibrillation on chr10q23." (PMID 32824463, 2020).
colon cancer (2 papers, 2019 to 2023). "According to the correlation analysis, as determined in the GSE14831 dataset, transfection of the HCT116 colon cancer cell line with miR-17-5p was associated with a marked downregulation of KCNMA1 expression." (PMID 30791468, 2019). "Therefore, treatment with AZA was associated with an increase in KCNMA1 expression in some colon cancer cell lines (i.e., SW620, SKCO1, COLO205, and SW480), while a lack of effect, or even a downregulation of KCNMA1, was instead observed for other cells lines, such as LOVO and COLO320." (PMID 30791468, 2019). "Additionally, PCA analysis of the KCNMA1-associated methylation revealed a high variance among colon cancer samples, which is reflected by the high variability of methylation observed in the 14 colon cancer cell lines analyzed." (PMID 30791468, 2019). "In accordance with the high variability in the methylation patterns of the KCNMA1 gene observed in primary human samples, marked differences in KCNMA1 gene methylation were observed in established colon cancer cell lines." (PMID 30791468, 2019). "Moreover, the association between KCNMA1, B3GNT6, and colon cancer needs to be explored further." (PMID 36944972, 2023). "We discovered new colon cancer related genes including AC007952.4, NEK8, CHRM3, ANO7, B3GNT6, NEURL1, ODC1 and KCNMA1." (PMID 36944972, 2023). "The lack of significant upregulation of KCNMA1 upon treatment of colon cancer cells with DAC can be explained in several ways." (PMID 30791468, 2019).
Dystonia (2 papers, 2023 to 2025). An abnormally increased muscular tone that causes fixed abnormal postures. "Although movement disorders are common in KCNMA1‐related disease, particularly in LoF variants, patients with isolated dystonia have not yet been reported." (PMID 40533913, 2025).
meningioma (2 papers, 2020 to 2025). A generally slow growing tumor attached to the dura mater. "KCNMA1 was demonstrated to be downregulated in grade III vs. grade I meningiomas using microarray expression profiles." (PMID 32596316, 2020). "Ten biomarkers, particularly AHCYL2, FGL2, and KCNMA1, were significantly related to grades and prognosis of meningioma." (PMID 32596316, 2020). "Though there were only four normal samples in GSE43290, the efficacy evaluation results still showed that five genes, including AHCYL2 (AUC = 0.729), FGL2 (AUC = 0.782), ID3 (AUC = 0.926), KCNMA1 (AUC = 0.745), and NMNAT2 (AUC = 0.851), could significantly distinguish meningiomas and normal samples." (PMID 32596316, 2020).
mesothelioma (2 papers, 2019 to 2023). A usually malignant and aggressive neoplasm of the mesothelium which is often associated with exposure to asbestos. "In mesothelioma cells, KCNMA1 knockdown induces a sustained increase in the basal [Ca2+]i." (PMID 31766522, 2019).
metastatic melanoma (2 papers, 2013 to 2021). A melanoma that has spread from its primary site to another anatomic site. "For instance, the miR-211-mediated down-regulation of the calcium ion-regulated potassium channel KCNMA1, whose expression is up-regulated in metastatic melanoma, was reported to account for the anti-invasive effects of this miRNA." (PMID 24039954, 2013). "In order to test whether the high expression and functionality of KCNMA1, KCNN4, and TRPM2 is specific to (primary) IGR39 cells, we analyzed several publicly available datasets on gene expression in melanocytes, as well as primary and metastatic melanoma cell lines." (PMID 34445066, 2021).
myopia (2 papers, 2013 to 2019). "KCNMA1 was identified as a susceptibility locus for SE and myopia in the wider general population in two previous large GWAS, but we observed much stronger effects and association near the high myopic end of the refraction spectrum." (PMID 31415580, 2019). "As the expression and role of GJD2 and RASGRF1 in eye and myopia development have been explored and reported previously, we focused on the gene expression of KCNMA1 in human ocular tissues." (PMID 31415580, 2019). "We found that KCNMA1 is linked to HM in highly myopic individuals with MMD in CREAM, a locus that had been previously identified for myopia in CREAM and 23andMe." (PMID 31415580, 2019). "Validation of the role of KCNMA1 in myopia progression is needed, particularly in ion channel activity which is one of the major functional pathways implicated, with an existing pool of several associated genes (KCNQ5, KCNJ2, and CACNA1D)." (PMID 31415580, 2019).
rheumatoid arthritis (2 papers, 2019 to 2024). A chronic, systemic autoimmune disorder characterized by inflammation in the synovial membranes and articular surfaces. "Expression of the KCNMA1 potassium channel gene was also raised, a finding that may have significance since potassium channels have been implicated in T cell autoreactivity in rheumatoid arthritis." (PMID 39566469, 2024).
transverse myelitis (2 papers, 2021 to 2022). "A variant within KCNMA1 gene has been associated with disability score as well as presence of transverse myelitis." (PMID 34675927, 2021). "One more to mention in this study was that a SNP rs1516512 in gene potassium calcium-activated channel subfamily M alpha 1 (KCNMA1) correlated with disability and transverse myelitis." (PMID 35498555, 2022).
type 1 diabetes (2 papers, 2020 to 2022). "It was hypothesized that the upregulation of KCNMA1 triggers an inflammatory response in PBMC from patients with type 1 diabetes." (PMID 36295826, 2022).
Achalasia (1 paper, 2016). A disorder of esophageal motility characterized by the inability of the lower esophageal sphincter to relax during swallowing and by inadequate or lacking peristalsis in the lower half of the body of the esophagus. "We observed a number of sequences involving the calcium signaling pathway (ie, CACNA1C, CACNB2, KCNMA1, CHRM2, CAV1, and NCS1) that were differentially expressed and were able to characterize these genes into possible functions related to achalasia pathogenesis." (PMID 27511445, 2016).
Allergy (1 paper, 2023). An allergy is an immune response or reaction to substances that are usually not harmful. "Cromolyn sodium, an FDA-approved anti-allergy drug involving in calcium ion transport, was predicted as a potential inhibitor for KCNMA1." (PMID 36763212, 2023).
amebic colitis (1 paper, 2015). "Paxilline was the most effective inhibitor in both IECs and macrophages, and the paxilline target, Kcnma1, was the third most down-regulated Kcn gene during acute amebic colitis." (PMID 26346926, 2015).
benign meningioma (1 paper, 2025). A grade I, slowly growing meningioma. "Lower KCNMA1 expression in high-grade compared to benign meningiomas has been previously reported in oligonucleotide microarray-based studies and this gene was also included in a 49-gene prognostic expression signature." (PMID 41154381, 2025).
colorectal adenocarcinoma (1 paper, 2019). The most common type of colorectal carcinoma. "Significantly lower levels of KCNMA1 (p < 0.001) were observed in patients with colorectal adenocarcinoma bearing microsatellite instability (MSI) as compared to healthy patients, and in neoplastic tissue as compared to healthy mucosa." (PMID 30791468, 2019).
COVID-19 (1 paper, 2024). A disease caused by infection with severe acute respiratory syndrome coronavirus 2. "In this study, we identified 156 shared genes between the COVID-19 and KIRC cohorts and selected four hub genes (GTSE1, CEACAM4, HECW2, and KCNMA1) as the foundation for developing a risk model." (PMID 38464749, 2024). "To identify potential drugs for the treatment of COVID-19 and KIRC co-morbidity, we conducted drug target enrichment analysis with four hub genes (GTSE1, CEACAM4, HECW2, and KCNMA1) as genetic targets associated with the construction of risk models via cellMiner and DsigDB databases." (PMID 38464749, 2024).
deafness (1 paper, 2015). An inherited or acquired condition characterized by the complete loss of the ability to hear from one or both ears. "In addition, KCNMB2 subunit interacts with KCNMA1, the α-subunit of potassium large conductance calcium-activated channel which also presents NIHL-associated polymorphisms and whose deletion produces progressive deafness." (PMID 26121033, 2015).
dysplasia (1 paper, 2019). A usually neoplastic transformation of the cell, associated with altered architectural tissue patterns. "In contrast, an important reduction of KCNMA1 expression levels in the colorectal mucosa can be observed starting from the fourth week of DSS/AOM administration, reaching statistical significance in the mucosa with high degree dysplasia (eighth week) (p = 0.01923)." (PMID 30791468, 2019).
dystrophinopathy (1 paper, 2022). "Among these genes, Pde4b is reported to affect the severity of dystrophinopathy, and Kcnma1, and Hs6st3 play roles in myogenesis." (PMID 36123393, 2022).
esophageal squamous cell carcinoma (1 paper, 2023). Esophageal squamous cell carcinoma (ESCC) is a type of esophageal carcinoma (EC) that can affect any part of the esophagus, but is usually located in the upper or middle third. "Besides, the upregulation of KCNMA1 has been observed to promote the reversal effect of verapamil on the chemoresistance to cisplatin in esophageal squamous cell carcinoma cells." (PMID 37812215, 2023).
gastric tumor (1 paper, 2017). "The subcutaneous xenograft tumor models were used to explore the effect of KCNMA1 on gastric tumor cell growth in vivo." (PMID 28231797, 2017).
gastrointestinal stromal tumor (1 paper, 2022). "Furthermore, the results revealed that two of the four central DEGs (ATP1A2, PLN, KCNMA1, and SCNN1B) of the PPI network were created in this module, thus suggesting that PLN and ATP1A1 may have a significant important role in gastrointestinal stromal tumors." (PMID 35655923, 2022).
growth deficiency (1 paper, 2022). "In a recent genetic study, several patients carrying loss-of-function mutations in the KCNMA1 gene encoding BK channel α subunit were characterized by a novel syndromic growth deficiency associated with severe developmental delay, cardiac malformation, bone dysplasia, and dysmorphic features." (PMID 35287796, 2022).
Hernia (1 paper, 2021). "The KCNMA1 gene (Potassium Calcium—Activated Channel Subfamily M α 1), which was upregulated in animals affected with hernia, and ACER2 (downregulated) were enriched in the apoptosis BP." (PMID 33513662, 2021). "The microtubule associated protein 1 light chain 3 γ (MAP1LC3C), vitrin (VIT), aggrecan (ACAN), alkaline ceramidase 2 (ACER2), potassium calcium-activated channel subfamily M α 1 (KCNMA1) and synaptopodin 2 (SYNPO2) genes are highlighted as candidates to trigger both types of hernia." (PMID 33513662, 2021).
hidradenitis suppurativa (1 paper, 2025). A chronic suppurative and cicatricial disease of the apocrine glands occurring chiefly in the axillae in women and in the groin and anal regions in men. "Potassium channels: Pain perception in hidradenitis suppurativa may be significantly influenced by the dysregulation of potassium channels, including genes such as KCNMA1, KCNQ5, KCNB2, KCND2, KCND3, and KCNAB3, all of which were identified in this study." (PMID 39940809, 2025).
intestinal pseudo-obstruction (1 paper, 2023). A type of ILEUS, a functional not mechanical obstruction of the INTESTINES. "We identified one VM patient with early onset intestinal pseudo-obstruction, megacystis, constipation, feeding difficulties and gastrointestinal dysmotility with a heterozygous KCNMA1 rare variant." (PMID 37288276, 2023).
ischemia reperfusion injury (1 paper, 2022). Adverse functional, metabolic, or structural changes in ischemic tissues resulting from the restoration of blood flow to the tissue (reperfusion), including swelling; hemorrhage; necrosis; and damage from free radicals. "In addition, other studies have suggested that KCNMA1-encoded cardiac BK channels provide protection against ischemia-reperfusion injury." (PMID 35368875, 2022).
liver disease (1 paper, 2025). "Interestingly, many of the genes linked to the differentially methylated CpGs have been associated with liver disease progression (eg, DCP2, TRPV3, ARRB1, KCNIP4, MIR10A) and cancer formation or progression (eg, MTHFR, GRIK2, GSN, HOX3, KCNMA1)." (PMID 40275933, 2025).
malignant glioma (1 paper, 2015). A grade III or grade IV glioma arising from the central nervous system. "Therefore, the down-regulation of KCNMA1 in malignant glioma is unlikely by chance." (PMID 26235283, 2015).
metastatic disease (1 paper, 2009). "Identifying organ-specific KCNMA1 gene involved in metastatic process, and developing targeted therapies against KCNMA1 will hopefully lead to better treatments for this deadly metastatic disease." (PMID 19640305, 2009).
nicotine dependence (1 paper, 2018). Physical and psychological dependence on nicotine. "A GWAS in Australian and Dutch populations identified SNPs in the KCNMA1 gene, which were significantly associated with nicotine dependence (rs592676, p = 8.91 × 10-6)." (PMID 29631575, 2018).
prostate (1 paper, 2013). "Among them, CRYAB, KCNMA1 and SDPR were overexpressed in all 3 reference tissues and could be considered as genes protective against PCa and therefore involved in the early stages of prostate carcinogenesis." (PMID 23840433, 2013).